MTOR (mechanistic target of rapamycin kinase)
Diseases named in the same sentence as MTOR in open-access papers (continued):
Sharing a sentence is not in itself a finding about the gene and the disease.
cytomegalovirus infection (continued). "Post-KT risk factors for PTDM have been reported to include immunosuppressive agents such as mTOR inhibitors and CNI, cytomegalovirus infection, graft rejection, and the following phenomena." (PMID 37819994, 2023). "Given that the UL38 protein has been reported to modulate mTORC1 activation, and mTORC1 activity is important for some metabolic changes during HCMV infection, we sought to determine if UL38’s metabolic reprogramming role is dependent on mTOR activation." (PMID 30677091, 2019). "Previous reports indicate that HCMV infection induces the levels of the Glut4 glucose transporter and the tuberous sclerosis protein (TSC1), a negative regulator of mTOR signaling." (PMID 22291597, 2012). "Though p-mTOR is induced during HCMV infection, studies have suggested that mTOR activity was not required at the late stage of virus replication." (PMID 36939350, 2023). "To test the role that mTOR plays in HCMV-induced modulation of central carbon metabolism, we assessed the impact of rapamycin treatment, an FDA approved mTORC1 inhibitor, on amino acid levels during HCMV infection." (PMID 30677091, 2019). "Likewise, NK cells from mice treated with rapamycin to block the mTOR pathway displayed defects in proliferation, and IFN-γ and granzyme B productions resulting in elevated viral burdens upon murine cytomegalovirus infection." (PMID 24795729, 2014). "However, HCMV infection can maintain mTOR activation during amino acid deprivation through viral UL38 protein binding and antagonizing the tuberous sclerosis subunit complex 2 (TSC2), a major suppressor of mTOR." (PMID 31594813, 2019).
gastric adenocarcinoma (32 papers, 2010 to 2025). "The aim of this study was to investigate whether the expression of MMP2, MMP7, and MMP9 in humans is associated with the expression of mTOR in its “naïve” and its phosphorylated (active) form in different topographical regions of gastric adenocarcinomas." (PMID 26652716, 2015). "For example, mTOR hyperactivation was reported in 60%–80% of all gastric adenocarcinomas, and inappropriate Akt and p-Akt expression in more than 74% of GC patients." (PMID 40260390, 2025). "Specifically, it was enriched in gastric adenocarcinoma (STAD) and linked to the NF-κB signaling pathway, mTOR signaling pathway, oxidative phosphorylation, mitosis, and DNA damage checkpoints." (PMID 39181686, 2024). "Results showed that this cotreatment modulated numerous critical proteins, such as EGFR/HER2/HER3, Kras/ERK/Vimentin, and mTOR/HIF1-α/HK2/LDHA pathways of gastric adenocarcinoma AGS cells." (PMID 36145507, 2022). "Strikingly, mTOR pathway activation, based on pS6 expression, was robustly activated in mouse gastric adenocarcinomas from the earliest stages of tumor development, and treatment with rapamycin impaired tumor growth." (PMID 26859571, 2016). "Our studies point to a stem cell origin for murine gastric adenocarcinomas and highlight the functional relevance of crosstalk between the Hh/Gli2 and mTOR pathways in cancer." (PMID 26859571, 2016). "Therefore, it is suggested that both DAG/PKCδ and IP3/Ca2+/CaMK IIβ operate in parallel to each other in PLCγ1-driven cell proliferation and migration of human gastric adenocarcinoma cells through Akt/mTOR/S6 pathway." (PMID 26633375, 2015). "Consequently, it is confirmed that the inhibition of PKCδ or CaMK IIβ could suppress the Akt/mTOR/S6 pathway in human gastric adenocarcinoma cells." (PMID 26633375, 2015). "In stomach adenocarcinoma, GPX3-driven oxidative stress mediates alterations in pyrimidine metabolism through the AMPK/mTOR signaling pathway." (PMID 41440040, 2025). "Our study addresses this gap by screening pairwise pharmacological interactions of EGFR, mTOR, and c-MET inhibitors with chemotherapeutics from five distinct groups in gastric adenocarcinoma cells, rigorously inspecting the kinetics of cell death." (PMID 39033209, 2024). "Molecular targets, such as epidermal growth factor receptor (EGFR), mammalian target of rapamycin (mTOR), and c-MET, have shown significant involvement in the aggressiveness of gastric adenocarcinomas." (PMID 39033209, 2024). "Using human gastric adenocarcinoma epithelial cell lines infected with H. pylori, Lee and his research team tested the effects of a carotenoid, astaxanthin, regarding P3K/AKT/mTOR and MMP expression." (PMID 38339127, 2024). "There remains an unmet need for patients with RCC, gastric adenocarcinoma (GC), and colorectal adenocarcinoma (CRC) who have progressed on previous vascular endothelial growth factor (VEGF)-targeted and mammalian target of rapamycin (mTOR) inhibitors." (PMID 37919668, 2023). "Published data point out their involvement in invasiveness and migration of tumor cells in the case of pancreatic and gastric adenocarcinoma, through the activation of the PI3-K/Akt/mTOR pathway." (PMID 34441296, 2021). "The involvement of Akt, mTOR, S6, and NF-κB signal molecules in regulatory mechanism of IP3/Ca2+/CaMK II and DAG/PKCδ axes in human gastric adenocarcinoma cells." (PMID 26633375, 2015). "Our previous study also showed that PLCγ1 activated mTOR signalling, which is known to be a negative autophagy regulator, in gastric adenocarcinoma cells." (PMID 29066806, 2017).
non-alcoholic fatty liver disease (32 papers, 2018 to 2025). "mTOR signaling has also been associated with non-alcoholic fatty liver disease (NAFLD)." (PMID 38892329, 2024). "For instance, metformin activates the AMPK/SIRT1/mTOR pathway, reduces oxidative stress, promotes autophagy, and inhibits apoptosis, thereby exhibiting therapeutic effects on non-alcoholic fatty liver disease." (PMID 39857404, 2025). "Thymoquinone has been reported to induce autophagy via the AMPK/mTOR/ULK1-dependent signaling pathway in C57BL/6 N mice with high-fat diet (HFD)-induced nonalcoholic fatty liver disease (NAFLD)." (PMID 40611111, 2025). "CAV1 was found to attenuate the Akt/mTOR pathway and hence alleviate lipid accumulation in non-alcoholic fatty liver disease." (PMID 39444451, 2024). "The differentially enriched DMR genes in the Lv-T vs. Lv-C comparison were enriched in non-alcoholic fatty liver disease (ko04932), the proteasome (ko03050), oxidative phosphorylation (ko00190), and the mTOR signaling pathway (ko04150)." (PMID 37511332, 2023). "Notably, USP5 expression was strongly correlated with the mTOR signaling pathway, nonalcoholic fatty liver disease, and salmonella infection." (PMID 40066708, 2025). "Moreover, in previous studies on non-alcoholic fatty liver disease, ITLN1 was shown to preserve protective autophagy through normalization of AMPKα/mTOR signaling, thereby alleviating cellular stress and lipid accumulation." (PMID 41218553, 2025). "EMPA was found to enhance hepatic macrophage autophagy by enhancing the AMPK/mTOR signaling pathway, thereby inhibiting the IL-17/IL-23 inflammatory axis, alleviating inflammation, and significantly improving liver injury in T2DM mice with non-alcoholic fatty liver disease (NAFLD)." (PMID 35814223, 2022).
papillary thyroid carcinoma (32 papers, 2011 to 2026). "We analyzed the association of mTOR expression with papillary thyroid cancer clinicopathological features, such as the TNM stage, BRAF V600E mutation, sex distribution, lymph node and distant metastases, and survival prognosis." (PMID 36980552, 2023). "Enhanced nuclear p-mTOR suggests the activation of the PI3K/Akt/mTOR pathway in aggressive variants of papillary thyroid carcinomas." (PMID 26793165, 2015). "P-mTOR has also been assigned to aggressive histological variants of papillary thyroid carcinoma and, thus nuclear labeling of p-mTOR has been discussed to serve as a diagnostic and prognostic marker as well as a potential therapeutic target." (PMID 24593867, 2014). "Our group also found in papillary thyroid carcinoma (that also presents frequent mutation in BRAF gene) an increased activation of mTOR pathway in BRAF mutated PTC, and in vitro transfection of BRAFV 600E disclosed a positive association between BRAF (over)expression and mTOR pathway activation." (PMID 23904987, 2013). "In conclusion, bavachinin exerts multi-targeted anti-cancer effects in papillary thyroid carcinoma cells by modulating PI3K/AKT/mTOR and MAPK/ERK pathways, suppressing pro-inflammatory cytokines, and inducing apoptosis." (PMID 41477125, 2025). "This systematic review summarized the available data on mTOR expression in papillary thyroid carcinoma." (PMID 36980552, 2023). "Mutations in the BRAF-V600E gene occur in approximately 45% of papillary thyroid cancers, while mutations in the RAS and ALK genes are frequently found These mutations drive mTOR pathway activation and lead to thyroid tumourigenesis." (PMID 37773165, 2023). "SQSTM1 has been suggested to regulate autophagy via the AKT/AMPK/mTOR signaling pathway to trigger autophagy and promote the growth of papillary thyroid cancer cells." (PMID 36559016, 2022). "In summary, WT1 contributes to cell proliferation, migration and growth of papillary thyroid carcinoma through augmented activation of the AKT/mTOR axis and ERK/p65 signaling pathway." (PMID 35123502, 2022). "Similar to the findings in this study, miR-718 supressed cancer cell metabolism and energy production in papillary thyroid cancer through regulating the PI3K/Akt/mTOR pathways." (PMID 35190587, 2022). "Rab22a can promote the EMT process and enhance proliferation, migration, and invasion of papillary thyroid carcinoma cells by activating the PI3K/AKT/mTOR signaling pathway." (PMID 35757470, 2022). "Therefore, mTOR inhibition is also a promising therapeutic target in the treatment of papillary thyroid carcinoma alone or in combination with inhibitors of other pathways." (PMID 36980552, 2023). "The mTOR inhibitors in clinical trials in differentiated thyroid cancer." (PMID 36980552, 2023). "Expression of mTOR was also somewhat higher in papillary carcinomas (P = 0.02)." (PMID 21834980, 2011). "Mechanistically, it inhibits the PI3K/AKT/mTOR and MAPK/ERK signaling pathways and downregulates pro-inflammatory cytokines, supporting its potential as a multi-targeted therapeutic candidate for papillary thyroid carcinoma." (PMID 41477125, 2025). "The same group demonstrated that aloperine regulated autophagy in multidrug-resistant ATC (MDR ATC) and multidrug-resistant papillary thyroid carcinoma (MDR PTC) cell lines via MAPK and PI3K/AKT/mTOR signaling pathways." (PMID 38791433, 2024). "This evidence is supported by a study in human papillary thyroid carcinoma, in which apatinib induced autophagy and apoptosis and limited tumour growth through the PI3K/AKT/mTOR pathways." (PMID 36983973, 2023).
papillary thyroid carcinoma (continued). "PV aqueous extract can inhibit the growth of papillary thyroid carcinomas through the induction of autophagy in vitro and in vivo, possibly due to being autophagy-mediated by the AMPK/ mTOR/ULK1 pathway." (PMID 36559016, 2022). "More recent preclinical studies have demonstrated that liraglutide may inhibit proliferation and migration in papillary thyroid carcinoma cell lines, potentially via PI3K/Akt/mTOR pathway modulation." (PMID 41376649, 2026). "The general pharmacological effects on human papillary thyroid cancer cells that are related to the activation of Sestrin2 (SESN2), upregulated p‐AMPK (phosphorylated AMPK), and inhibits p‐mTOR (phosphorylated mTOR) and p‐p70S6Kinase (ribosomal protein S6 kinase)." (PMID 38230908, 2024). "In terms of signaling molecules, metformin also appeared to inhibit expression of total mTOR within BCPAP papillary thyroid cancer cells and increased expression of total mTOR in 8505c cells, regardless of the presence of vemurafenib." (PMID 26284586, 2015). "The combination of lenvatinib with other targeted agents, such as mTOR inhibitors, is a promising area of investigation, while MEK inhibitors, BRAF inhibitors and immune-oncology agents also show promise for treating radioiodine-refractory, differentiated thyroid cancer." (PMID 31093354, 2017).
sarcoidosis (32 papers, 2017 to 2025). Sarcoidosis is a multisystemic disorder of unknown cause characterized by the formation of immune granulomas in involved organs. "Whole-exome sequencing (WES) analysis of familial forms of sarcoidosis has suggested that genetic variants encoding regulators of mTOR and autophagy-related proteins can be disease-causing." (PMID 40996589, 2025). "Deregulation of Rac1-related pathways including mTOR appears to be a relevant predisposing factor for familial sarcoidosis." (PMID 34440765, 2021). "A next generation sequencing study of five French families with familial sarcoidosis revealed inherited pathogenic variants of genes encoding mammalian target of rapamycin complex 1 (mTORC1) and mTOR complex." (PMID 33036432, 2020). "While this familial analysis confirms the genetic heterogeneity commonly reported in sarcoidosis, it allowed to stratify heritable pathogenic variants in mTOR and Rac1 signalling pathways, as well as in autophagy and vesicular transport processes." (PMID 32823753, 2020). "Another major pathway implicated in sarcoidosis is the mammalian target of rapamycin (mTOR) pathway which plays a critical role in cell nutrition and immune responsiveness." (PMID 33036432, 2020). "metabolic alterations in monocytes have been identified as another hallmark, PBMCs from sarcoidosis patients show dysregulation of metabolic and oxidative phosphorylation pathways, particularly upregulation of the mechanistic target of rapamycin (mTOR) signaling pathway." (PMID 41169375, 2025). "Familiar sarcoidosis has been associated with mutations in the mTOR regulators." (PMID 40002701, 2025). "In addition, we have identified aberrant mTOR signaling as one of the top enriched pathways found in rare genetic variants identified in familial sarcoidosis patients." (PMID 38353578, 2024). "Additionally, progesterone has been shown to inhibit the mTOR pathway, which has been implicated in the development of sarcoidosis." (PMID 38212490, 2024). "Uninhibited mTOR signalling in macrophages has already been shown to be a feature of excessive granuloma formation, making this a particularly interesting pathogenic pathway for progressive fibrotic sarcoidosis." (PMID 36543347, 2022). "Using whole-exome sequencing of familial sarcoidosis, researchers have identified genetic mutations in essential factors that regulate autophagy, such as the mammalian target of rapamycin (mTOR) and Rac1 molecular hubs, that result in constitutional defects in the regulation of macroautophagy." (PMID 35615369, 2022). "Although Linkeet al.'s study on mTOR signalling in the persistence of granuloma was wholly done in murine models, an association with sarcoidosis was shown via interrogation of the transcriptomic data from Lockstoneet al.’s progressive fibrotic versus self-limiting dataset in the lungs." (PMID 36543347, 2022). "Despite the difference in the two gene set sizes (329—F-SARC and 5341—CONTROL), we estimate that our previous data linking the predisposition to inherited sarcoidosis to Rac1- and mTOR-related molecular hubs was confirmed in the 13 families analyzed in the present study." (PMID 34440765, 2021). "This review synthesizes evidence on the effectiveness and safety of the mTOR inhibitor sirolimus in varying forms of sarcoidosis." (PMID 40996589, 2025). "It is well-established that chronic signaling through the metabolic checkpoint kinase mTOR promotes macrophage granuloma formation and is an indicator of sarcoidosis progression." (PMID 41476976, 2025). "A single-centre trial and several case reports have demonstrated the promising effectiveness and safety of mTOR inhibition as a therapeutic approach for sarcoidosis." (PMID 39904950, 2025). "In a murine model of sarcoidosis, mTOR activation leads to spontaneous generation of skin granulomas, and in pulmonary sarcoidosis in humans, activated mTOR signaling is associated with progressive disease." (PMID 36902053, 2023).